TNF (tumor necrosis factor)
Diseases named in the same sentence as TNF in open-access papers (continued):
Sharing a sentence is not in itself a finding about the gene and the disease.
Insulin resistance (continued). "Results of 252 common targets were listed as (related with T2DM); TNF signaling pathway, insulin resistance, apoptosis, HIF-1 signaling pathway, PI3K-Akt signaling pathway, FoxO signaling pathway, insulin signaling pathway and type 2 diabetes mellitus." (PMID 33150068, 2020). "Two recent meta-analyses indicated that both patients with type 1 and type 2 DM have significantly elevated levels of serum TNF-α which showed a positive correlation with insulin resistance." (PMID 32089876, 2020). "For instance, the anti-inflammatory cytokine IL10 prevents TNFα-induced insulin resistance in adipocytes." (PMID 32408016, 2020). "Two studies regarding the effects of pioglitazone and different doses L. casei in diabetic mice showed comparable reductions in insulin resistance, TNF-α and IL-6 at 109 CFU dose." (PMID 33292434, 2020). "It is known that adipose tissue increases the secretion of proinflammatory cytokines, such as IL-6, TNF-α, and leptin, which are closely related to the development of insulin resistance." (PMID 32694929, 2020). "SQC can improve the insulin resistance of DM by affecting the TNF signal pathway, which is consistent with the previous clinical research results." (PMID 32595730, 2020). "In mammals, interleukin-6 (IL6) and tumor necrosis factor have been proven to induce hepatic insulin resistance through the suppression of the cytokine signaling (SOCS3) pathway." (PMID 32754117, 2020). "In the present study, adipocytes were treated with TNF-α for 24 h to induce insulin resistance, which exhibited impaired insulin-stimulated glucose uptake and insulin signaling." (PMID 33390968, 2020). "Two studies showed that insulin resistance and type 2 diabetes are associated with higher levels of C-reactive protein (CRP), interleukin-6 (IL-6), and tumour necrosis factor-α (TNF- α), which are markers of subclinical systemic inflammation." (PMID 32369922, 2020). "RA patients with ε2ε3 genotype are associated with lower levels of TNF-α, IL-6, resistin, visfatin, and CVD risk, while RA patients with ε3ε4 genotype exhibited higher levels of LDL-C, insulin resistance, and higher CVD risks." (PMID 33297350, 2020). "Studies shows that the key pro-inflammatory cytokines driving insulin resistance are TNFα and IL1β secreted by local macrophages." (PMID 32085416, 2020). "Specifically, the proinflammatory cytokine TNF-α has been reported to induce insulin resistance, and previous studies have established the role of inflammatory cytokines IL-1β and IL-6 in the development and progression of T2DM." (PMID 32132984, 2020). "Tumor necrosis factor-α (TNF-α), which is overexpressed in obese humans and rodents, plays a central role in metabolic inflammation and insulin resistance." (PMID 33033337, 2020). "Some in vivo and in vitro studies have shown that tumor necrosis factor-α (TNF-α) induces insulin resistance to some extent, through the inhibition of intracellular signaling from the insulin receptor." (PMID 31803921, 2019). "Evidence suggests that TNF is involved in insulin resistance in humans and animal adipose tissue and blocks reversion of the diabetic condition by masking the activity of NF-кB." (PMID 31842333, 2019). "Compared with normal backfat thickness sows, the excessive backfat thickness sows had increased levels of plasma glucose, IL-6, and TNF-α and homeostasis model assessment insulin resistance values." (PMID 31881697, 2019). "Oxidative stress destroys adipose tissue to release adipocytokines such as TNF-α and IL-6α to trigger inflammation and is involved in the pathogenesis of insulin resistance." (PMID 31073335, 2019). "Binding of TNF-α with its soluble receptor results in a decrease in insulin resistance in obese animals." (PMID 31597283, 2019). "To better understand the roles played by insulin and TNF-α in insulin resistance, we performed proteomic analysis of differentiated 3T3-L1 adipocytes treated with insulin (Ins), TNF-α (TNF), and both (Ins + TNF)." (PMID 31635166, 2019).
Insulin resistance (continued). "TNF-α and saturated free fatty acids (FFAs) are increased in obese humans and correlate with insulin resistance." (PMID 31443599, 2019). "As well, increased levels of proinflammatory cytokine TNF-α have been found to correlate with insulin resistance." (PMID 31546972, 2019). "Together with TNFα and IL-6, IL-1α/β, in turn, contributes to the development of insulin resistance in adipocytes through downregulation of insulin receptor substrate-1 expression, thereby facilitating accumulation of lipids in the liver." (PMID 31507607, 2019). "Over-expressed MKK6/3-p38/MAPK in L6 myotubes was reported to deteriorate the action of GLUT4 via down-regulation of GLUT4 gene expression, whereas knock-down MAP4K4, the upstream kinase of ERK1/2 and JNK, inhibits TNF-α-induced insulin resistance." (PMID 29955954, 2019). "A meta analysis of effects of probiotic on NAFLD/NASH showed that probiotic therapies can reduce liver aminotransferases, total-cholesterol, TNF-α, and improve insulin resistance in NAFLD/NASH patients." (PMID 30658519, 2019). "Adiponectin can act as an insulin sensitizer, while pro-inflammatory cytokines, such as TNF-α and IL-6, contribute to insulin resistance." (PMID 31731774, 2019). "Among those, TNF-α, specifically, has been shown to be directly involved in the development of hepatic steatosis and insulin resistance." (PMID 31949886, 2019). "Elevated levels of TNF-α are particularly inflammatory with several studies showing a direct correlation between TNF-α and insulin resistance." (PMID 31443599, 2019). "Cellular metabolic pathways and mechanisms of TNF-α mediated insulin resistance are unclear, and in many cases, contradictory." (PMID 31635166, 2019). "This indicates the etiological role of elevated palmitate on TNF-α overexpression in obese insulin resistance hepatocytes." (PMID 30863203, 2019). "It has been shown that systemic inflammation induces insulin resistance because inflammatory cytokines such as tumor necrosis factor-α (TNF-α) inhibits insulin receptors." (PMID 31142015, 2019). "For instance, proinflammatory cytokines such as TNF-α, secreted locally by adipose tissue macrophages, have been found to be likely mediators of insulin resistance." (PMID 31015797, 2019). "Adipose tissue-secreted TNF-α has been shown to induce insulin resistance in animal models through activation of Janus N kinases (JNK) and serine phosphorylation of insulin receptor substrate (IRS)." (PMID 31885787, 2019). "Primary hepatocytes and C57BL/6J wild-type mice treated with TNF-α exhibited marked hepatic insulin resistance." (PMID 31866871, 2019). "Several genetic and environmental factors have been determined to involve in insulin resistance, of which TNF-α has taken much concentration recently." (PMID 30863203, 2019). "Free fatty acids cause an inflammatory response, and macrophages release more TNF-α to induce insulin resistance in adipose and liver tissues." (PMID 31083505, 2019). "The IKK complex inhibits NF-κB, the nuclear factor that stimulates secretion of inflammatory cytokines like IL-1, IL-6 (which are also known to induce insulin resistance) and TNFα." (PMID 31466350, 2019). "Inflammatory cytokines (e.g., TNFα, tumor necrosis factor α) and fatty acids are released from adipose tissue and serve as the major contributors to induce insulin resistance." (PMID 31814873, 2019). "Resveratrol supplementation in obese men for 1 month reduced glucose, insulin resistance index and leptin level and lowered inflammatory markers (e.g., TNF-α, leukocytes)." (PMID 30931309, 2019). "The role of TNF-α in insulin resistance of adipocytes and in the stimulation of lipolysis indicates hyperlipidemia and peripheral insulin resistance." (PMID 30863203, 2019). "NF-kβ and TNF-α are critical mediators of insulin resistance and beta cells dysfunction in the pancreas, contributing to the development of diabetes mellitus, and also anomaly in lipid metabolism." (PMID 31708869, 2019).
Insulin resistance (continued). "It has been shown that TNF-α contributes to insulin resistance through impairment of insulin signaling by increasing serine phosphorylation of insulin receptor substrate- (IRS-) 1 and diminishing insulin receptor (IR) tyrosine kinase activity." (PMID 31828161, 2019). "Palmitate generate ceramide which triggers mitochondrial oxidative stress and insulin resistance, and the role of TNFα in the generation of insulin resistance was also shown." (PMID 31814873, 2019). "These phenomena are accompanied by abnormal release of FA, adipokines, and proinflammatory molecules including TNFα, interleukin (IL)-6, and IL-1β which, by acting on target organs, induce insulin resistance and favor the onset of type 2 diabetes." (PMID 31781039, 2019). "The TNFα treatment in 3T3-L1 cells and rats induces insulin resistance, whereas the suppression of TNFα and receptor genes improves insulin sensitivity in ob/ob rodent model." (PMID 31130918, 2019). "Flavonoids morin, hesperidin, rutin, (rats), and chrysin (mice) were effective in reducing inflammatory cytokines IL-1β, IL-6, and TNF-α in diabetic animals, significantly improving hyperglycemia, glucose intolerance, and insulin resistance." (PMID 30764536, 2019). "Increased production of TNFα and NEFAs by adipose tissue induces insulin resistance by suppressing tyrosine phosphorylation of IR or IRS-1, leading to abnormal metabolic activity in the liver, skeletal muscle, and adipose tissue." (PMID 31581253, 2019). "It is well known that TNF-α promotes insulin resistance by inhibiting IRS1 (insulin receptor substrate 1) and IL-1β causes apoptosis in β-pancreatic cells, thereby diminishing insulin production." (PMID 31430882, 2019). "As a large amount of FFA, resistin, TNF-α, interleukin 6 and other compounds released by oversized adipose tissue can produce insulin resistance." (PMID 31801571, 2019). "Taken together, these data demonstrate that normalized insulin-signaling pathway by both EWH and IRW is a contributing factor to the improved glucose uptake in TNF-α-induced insulin resistance." (PMID 29955954, 2019). "The idea is consistent with the previous studies regarding elevated expression of TNF-α in the liver and skeletal muscle in palmitate-induced insulin resistance condition." (PMID 30863203, 2019). "Collectively, these then produce greater amounts of pro-inflammatory cytokines, namely IL-1β, IL-6, and TNFα as well as chemokines such as MCP-1, which are causally associated with insulin resistance, dyslipidemia, and metabolic disease." (PMID 30736459, 2019). "Pro-inflammatory cytokines, including interleukins 6 and 8 (IL-6 and IL-8) and tumor necrosis factor-α (TNFα), are key players in the onset of insulin resistance." (PMID 31849810, 2019). "Further, FGF-1 treatment significantly represses TNF-α-induced insulin resistance in vitro and in vivo." (PMID 31866871, 2019). "Physical activity increases the secretion of interleukin-6 (IL-6) from muscle cells, which has anti-inflammatory effects through inhibition of TNF-a and IL-1b, and reduces TNF-induced insulin resistance." (PMID 30867683, 2019). "TNF-α is mainly produced in adipocytes and induces tissue-specific inflammation and insulin resistance through a reduction in GLUT4 expression." (PMID 30850679, 2019). "Cytokines, including FasL, TNF α, and IL-6, play important roles in the induction of β-cell apoptosis as well as insulin resistance." (PMID 30953496, 2019). "We even demonstrate the co-existence of this pro-TNF inflammatory state in individuals with metabolic syndrome and insulin resistance." (PMID 31178745, 2019). "As per the previous literature, TNF-α induces insulin resistance by inhibiting IRS-1 phosphorylation and GLUT-4 expression, and elevated in patients with heart failure, and myocardial ischemia reperfusion." (PMID 30674322, 2019).
Insulin resistance (continued). "TNF-α and IL-6 are the most important pro-inflammatory mediators responsible for inducing insulin resistance in adipocytes and peripheral tissues." (PMID 30871060, 2019). "Serum TNFα level and insulin resistant status (HOMR-IR) were higher in RSA group than in control group (p = 0.038, 0.001, respectively)." (PMID 31200713, 2019). "We found that platelet 5HT levels were positively correlated with plasma TNFα concentrations, a proinflammatory adipokine present in higher levels in obese individuals and subjects with insulin resistance." (PMID 31192261, 2019). "Based on these results, it can be inferred that there is COX-2 activation of visceral fat induced insulin resistance through the generation of systemic inflammatory TNF-α." (PMID 31466366, 2019). "It is known that, in obese subjects, chronic inflammation is observed, with increased levels of proinflammatory cytokines, including IL-6 and tumor necrosis factor-n (TNFα), which increase insulin resistance." (PMID 31001554, 2019). "Resistin is a pro-inflammatory adipokine, in addition it regulates insulin resistance and inflammation via IL-6 and TNF secretion from macrophages." (PMID 31788033, 2019). "The role of TNF-α in insulin resistance seems to be related to a reduced expression of the insulin-sensitive glucose transporter GLUT4." (PMID 31835864, 2019). "In humans, circulating TNFα levels increase with aging, suggesting a correlation between vascular insulin resistance and plasma TNFα levels." (PMID 31861196, 2019). "Another point is that TNFα promotes insulin resistance through the phosphorylation of insulin receptor substrate 1 via the activation of cellular stress-responses kinases." (PMID 31349552, 2019). "TNF-α is a major player mediating the activation of signaling cascades in adipocytes that are central to inflammation and insulin resistance." (PMID 31100089, 2019). "For example, factors that are known to be related to insulin resistance, such as hyperinsulinemia and TNF-α, counter-regulate expression of resistin mRNA and protein in cultured adipocytes." (PMID 30886868, 2019). "M1 macrophages in adipose tissue produce pro-inflammatory cytokines such as TNFα, which induces insulin resistance and suppresses the expression of PPARγ3." (PMID 30760783, 2019). "Anti-TNF-α antibody administration attenuated hepatic insulin resistance and progression of hepatic steatosis in a mouse model." (PMID 31001563, 2019). "TNF predominantly induces insulin resistance by serine phosphorylation of insulin receptor substrate-1, which is also a potent activator of NF-кB." (PMID 31842333, 2019). "The inflammatory milieu heightens the expression and release of proinflammatory cytokines, such as TNFα and IL-1β, which play a key role in damnification of insulin signaling, leading to insulin resistance and subsequently promoting NAFLD." (PMID 31215394, 2019). "The role of EWH and IRW in preventing TNF-α-induced insulin resistance was studied by co-incubation of TNF-α in the presence of EWH or IRW." (PMID 29955954, 2019). "Circulating levels of IL-6 and TNF-α are elevated in obese individuals and patients with insulin resistance." (PMID 31398785, 2019). "Taken together, our data demonstrated that naringenin ameliorated TNF-α-induced insulin resistance in an AMPK-depended manner." (PMID 31591391, 2019). "A study conducted on obese rats with insulin resistance, showed that the neutralization of TNFα with a soluble fusion protein, IgG-tumor necrosis factor receptor (TNFR), increases insulin sensitivity and restores plasma insulin values close to normal levels." (PMID 31344895, 2019). "This is because IL-17 also induces the production of IL-6 and TNF-alpha, the cytokines with marked proinflammatory effects that play an important role for the development of insulin resistance." (PMID 30862094, 2019). "A number of studies have described the direct role for TNF-α in the pathophysiology of insulin resistance." (PMID 31591391, 2019).
Insulin resistance (continued). "EVs harvested from adipose tissue from obese ob/ob mice have been found to induce macrophage activation, proinflammatory cytokine release such as IL-6 and TNFα, as well as promoting insulin resistance when injected into wildtype mice." (PMID 30736459, 2019). "The overproduction of inflammation cytokines, in particular tumor necrosis factor-α (TNF-α) and interleukin-6, have been found to be associated with insulin resistance and the initiation and development of DM and cancer." (PMID 31847392, 2019). "The adipocyte hypertrophy and TNF-α secretion are the most relevant contributors to the development of insulin resistance in adipose tissue." (PMID 30813339, 2019). "Macrophages begin to form so-called crown-like structures in adipose tissue and start to produce the proinflammatory cytokines involved in inflammatory responses and in insulin resistance, such as TNF-α, IL-1β and IL-6." (PMID 31363792, 2019). "Neutralization or knockdown of inflammatory mediators, including TNF-α and IL-6, are protective against insulin resistance in obese rodents." (PMID 31075962, 2019). "HFF rats also showed hepatic insulin resistance, together with an increase in plasma triglycerides, cholesterol, and tumor necrosis factor alpha." (PMID 31694213, 2019). "It was reported that TNF-α expression was elevated in the blood of type 2 diabetic patients, resulting in an inflammatory response and insulin resistance." (PMID 30974824, 2019). "We used the model to simulate the dynamics of gene expression induced by different combinations of the five input signals, i.e. ER stress, oxidative stress, and cytokines (TNF α, FasL, IL-6), which serve as triggers for insulin resistance and β-cell apoptosis." (PMID 30953496, 2019). "Decreased IRS-1 serine phosphorylation is associated with negative effects on the insulin signaling pathway and has been described in connection with TNF-α-induced insulin resistance." (PMID 30863203, 2019). "For instance, decreased adiponectin and increased TNFα and IL-6 are contributed to insulin resistance development." (PMID 32133054, 2019). "In this review, we summarize the molecular mechanisms of insulin resistance in aged/senescent and TNFα-stimulated endothelial cells mediated by gangliosides and highlight the possible roles of gangliosides in vascular insulin resistance-related diseases." (PMID 31013778, 2019). "Expression of the two most important pro-inflammatory cytokines, TNF-α and IL-6, is enhanced by the elevation of fat and insulin resistance in the body." (PMID 31597283, 2019). "As a result of this inflammation, the synthesis of pro-inflammatory cytokines (TNF-alpha, IL-6, and IL-1β) becomes increased and insulin resistance develops." (PMID 30881343, 2019). "The most important role of MCP-1 is to regulate the migration and infiltration of monocytes and macrophages, but it can also contribute to insulin resistance, acting together with other mediators such as IL-6 and TNF-α." (PMID 31438590, 2019). "More specifically, TNF-α has been proposed as a link between adiposity and the development of insulin resistance, given its high expression in the AT of subjects with obesity." (PMID 30850679, 2019). "The beneficial effect of probiotics on the levels of alanine aminotransferase, AST, TC, HDL, tumor necrosis factor-α and also on insulin resistance (assessed in a homeostasis model (HOMA-IR)) have been reported earlier." (PMID 30923658, 2019). "M1 macrophages are host-defense cells that kill pathogens and secrete proinflammatory cytokines such as TNF-α and IL-6, both of which contribute to insulin resistance." (PMID 31577826, 2019). "TNF-α was observed to be increased in adipose tissue and correlated with insulin resistance; ablating TNF-α was shown to decrease insulin resistance in animal models." (PMID 31253200, 2019).